SERPINE2 (serpin family E member 2)
Diseases named in the same sentence as SERPINE2 in open-access papers (continued):
Sharing a sentence is not in itself a finding about the gene and the disease.
cancer (45 papers, 2010 to 2026). A tumor composed of atypical neoplastic, often pleomorphic cells that invade other tissues. "Concurrently, as a secreted factor, SERPINE2 promotes cancer-associated fibroblast activation, M2 macrophage polarization, extracellular matrix remodeling, and angiogenesis, collectively fostering immune suppression and metastatic persistence." (PMID 42099617, 2026). "The incidence of various cancers is closely associated with SERPINE2 expression, making it crucial to explore its regulatory mechanism in vivo." (PMID 40463876, 2025). "SERPINE2 is upregulated in aggressive variants of several cancer types, and high expression levels correlate with poor prognosis in patients." (PMID 38634469, 2024). "Specifically, we found that SERPINE1 and SERPINE2 were significantly positively associated with stromal score and immune score in most cancers." (PMID 38274096, 2023). "Following ATF3 expression, SERPINE2 causes the improvement of cell colony-forming capacity and is thus involved in the control of cancer growth." (PMID 37124542, 2023). "Numerous studies have reported SERPINE2 overexpression in various cancers, which has been associated with the degree of cancer malignancy." (PMID 34679626, 2021). "SERPINE2 was implicated in modulating DNA damage response and favoring cancer cell invasion." (PMID 40698088, 2025). "Recent research has demonstrated the pro-cancer potential of Serpine2 when functioning from an exosome." (PMID 40642075, 2025). "Our results indicate that in the SERPINE gene family, SERPINE1 is highly expressed in pan cancer cells, followed by moderate expression of SERPINE2, while SERPINE3 shows low expression." (PMID 40463876, 2025). "We found macrophages induced by SERPINE2 in co-culture with cancer cells accelerated cancer cell proliferation and migration." (PMID 40463876, 2025). "In summary, our study reveals that SERPINE2 promotes the phenotypic transformation of TAMs, establishing a new positive feedback loop between cancer cells and TAMs." (PMID 40463876, 2025). "In terms of TMB, SERPINE1, SERPINE2, and SERPINE3 were found to associated with TMB in seven cancers, fourteen cancers, and four cancers, respectively." (PMID 38274096, 2023). "In any case, our identification of SERPINE2 from an unbiased analysis for malignant cells of RCC patients provides a novel sight into the programs of human cancers and metastasis for future research." (PMID 36646679, 2023). "Whereas the abnormal expression of SERPINE2 was related to fifteen different cancers, twelve of which were upregulated and three were downregulated." (PMID 38274096, 2023). "Metastatic cancer cells that intravasate into the vasculature secrete Serpin Family E Member 2 (SERPINE2) and secretory leukocyte protease inhibitor (SLPI) to promote metastasis." (PMID 36046433, 2021). "The cell number was significantly decreased in cancer cells with SERPINE2 downregulation (P < 0.05)." (PMID 33317533, 2020). "Kaplan–Meier survival analysis showed that the expression levels of COL1A1, COMP, and SERPINE2 significantly correlated with cancer-specific survival and overall survival of BC patients." (PMID 32850407, 2020). "Precisely, these genes intersected for 21 candidate targets, among which IL11 and SERPINE2 were most relevant to cancer-promoting inflammation." (PMID 31735169, 2019). "One example is the SERPINE2, which can lead to metastasis or apoptosis of cancer cells under different conditions." (PMID 29844359, 2018). "SerpinE2 overexpression plays an important role in malignant progression and metastasis in different cancer types." (PMID 27793045, 2016). "The extracellular serine protease inhibitor (serpin) serpinE2, also known as PN-1, is overexpressed in various human cancers, including breast and plays an essential role in malignant progression and metastasis." (PMID 27793045, 2016).
cancer (continued). "Serpin peptidase inhibitor, clade B member 2 (SERPINE2) or plasminogen activator inhibitor type 2 (PAI2) is involved in cancer invasion and metastasis by controlling serine protease urokinase plasminogen activator." (PMID 20096135, 2010). "Targeting SERPINE2 may therefore represent a paradigm shift in advanced cancer therapy by simultaneously disrupting oncogenic persistence, genome maintenance, and immune exclusion." (PMID 42099617, 2026). "Among these, SERPINE2 has emerged as a convergent mediator across diverse cancer types." (PMID 42099617, 2026). "Current research indicates a high expression of SERPINE2 in many cancers." (PMID 40463876, 2025). "For example, serine proteinase inhibitor clade E member 2 (SERPINE2, also known as plasminogen activator inhibitor type 1) acted as oncogenes and promoted the proliferation, metastasis, or stemness behavior in various types of cancers." (PMID 37280069, 2023). "SERPINE2 is also commonly upregulated in lung, colorectal and pancreatic carcinoma." (PMID 36646679, 2023). "Recent studies have reported that SERPINE2 contributes to the development of various cancers." (PMID 34679626, 2021). "SERPINE2 expression in the cytoplasm of the cancer cells was observed in 19 of the 74 cases (26%)." (PMID 33317533, 2020). "Removal of IL11 abrogated the growth competitiveness of YTHDF2-deficient SMMC7721 cells, while a SERPINE2 deficit attenuated the proangiogenic capacity of SMMC7721 cells, highlighting that IL11 and SERPINE2 are key targets of YTHDF2 in cancer-promoting inflammation." (PMID 31735169, 2019). "Although there is some evidence in the literature suggesting that serpinE2 may play a role in carcinogenesis, the precise function of this serpin in cancer still remains elusive." (PMID 20942929, 2010). "In addition, co-culture with macrophages induced by SERPINE2 recombinant protein may promote the proliferation and migration of cancer cells." (PMID 40463876, 2025). "Hence, SERPINE2 is regarded as a driver of metastatic progression in human cancer." (PMID 36797769, 2023). "Thus, SERPINE2 has a dual role in cancer progression and its role in OS progression, probably uPA/uPAR independent, may be further investigated." (PMID 23213280, 2012). "Our results indicated that SERPINE1 was highly expressed, SERPINE2 was moderately expressed, and SERPINE3 was lowly expressed in pan-cancer." (PMID 38274096, 2023). "A paralog of SERPINE1, SERPINE2, has been recently reported to participate in DNA repair process through the direct interaction with ATM and MRE11 to protect cancer cells from IR-induced DNA damage." (PMID 36681663, 2023). "YTHDF2 promotes the decay of m6A-containing IL-11 and serpin family E member 2 (SERPINE2) mRNAs, which are involved in inflammation-mediated malignant tumors and the destruction of normal blood vessels." (PMID 34150765, 2021). "A recent study showed that SERPINE2 and SLPI are produced in cancer tissues and are overexpressed under tumorigenic conditions." (PMID 28255192, 2017). "SERPINE2 and SLPI have also been postulated as new molecular targets in the therapy of certain cancers." (PMID 28255192, 2017). "Hence, serpinE2 may also be a potential therapeutic target for cancer treatment." (PMID 20942929, 2010). "The results displayed that SERPINE2 was highly expressed in cancer tissues compared to non-neoplastic adjacent tissues." (PMID 40463876, 2025). "Together, the double-inhibitory mechanism involving the molecular interaction of SERPINE2, HTRA1, and SDC4 as suggested here for NC cell migration in the Xenopus embryo might also regulate cancer cell migration in human metastasis." (PMID 38634469, 2024). "A small subset of mesenchymal genes (CDH2, DKK1, SERPINE2, MATN3, APLP1, CXCL1, FOXC2, BMP1) in Basal BRCA has been validated in this PRC2+-CGI pool with SERPINE2 and CXCL1 being the 2 most commonly overlapping genes found in 7 and 6 cancer types, respectively." (PMID 38902393, 2024).
cancer (continued). "SERPINE2 and MFAP5 have both been reported to promote the EMT process in cancer." (PMID 37283740, 2023). "Interestingly, several genes, such as DRAM1, SERPINE2, SDC2 and CTSB, have been shown to correlate with chemotherapy efficiency in cancers 20-24." (PMID 31660072, 2019). "In YTHDF2-deficient cells, re-expression of wild-type YTHDF2 but not the catalytically inactive mutant offset the acquired cancer-promoting inflammatory phenotypes, and reduced both phosphorylation of STAT3 and stabilization of IL11 and SERPINE2 mRNAs." (PMID 31735169, 2019).
infection (4 papers, 2020 to 2025). The state of being infected such as from the introduction of a foreign agent such as serum, vaccine, antigenic substance or organism. "We used the lentiviral vector containing SERPINE2 to infect the LF cells to overexpress the SERPINE2 in LF cells, and the protein level of SERPINE2 was significantly increased after the infection." (PMID 39754051, 2025). "Moreover, the authors found that the antiviral effects of SERPINA1, SERPINE1, SERPINE2, and SERPINF1 were observed during the first steps of infection in HBEC ALI cultures, revealing reduced SARS-CoV-2 entry into target cells." (PMID 38601158, 2024).
adenocarcinoma (2 papers, 2020 to 2022). A common cancer characterized by the presence of malignant glandular cells. "SERPINE2 is differentially expressed in many tumors and their corresponding normal tissues and is highly expressed in adenocarcinoma, especially enriched in glandular organs of the digestive system and highly expressed in liver tumors." (PMID 36505099, 2022).
immune system diseases (1 paper, 2018). "DEGs that enriched to “immune system diseases” played critical roles in cell-matrix communication (THY1, LVRN, LUM, TIMP3, SPOCK1, LGALS3BP, FAT2, and SERPINE2) as well as inflammation (IL1R2, CD22, PTGES, TNFSF10, IL2RB, C3, SERPING1, and IL-17RE)." (PMID 30131724, 2018).
SERPINE2 also shares sentences with these, for which no sentence is quoted: oral squamous cell carcinoma (5 papers); renal cell carcinoma (3); brain ischemia (2); esophageal cancer (2); hemangioma (2); non-small cell lung carcinoma (2); type 2 diabetes (2); vascular disorder (2); Airway obstruction (1); Allergy (1); aortic aneurysm (1); astrocytomas (1); benign tumors (1); Bladder Urothelial Carcinoma (1); cardiac interstitial fibrosis (1); cartilage disease (1); Cerebral ischemia (1); cholangiocarcinoma (1); CNS tumors (1); corneal disease (1); coronary artery disease (1); endocrine system disease (1); ependymoma (1); female infertility (1); heart failure (1); Hypertension (1); idiopathic pulmonary fibrosis (1); Insulin resistance (1); ischemia (1); joint degenerative diseases (1).
A further 21 diseases each share a sentence with SERPINE2 in 1 paper.